SIRT6 (sirtuin 6)
Diseases named in the same sentence as SIRT6 in open-access papers (continued):
Sharing a sentence is not in itself a finding about the gene and the disease.
Stroke (12 papers, 2014 to 2025). Sudden impairment of blood flow to a part of the brain due to occlusion or rupture of an artery to the brain. "When ECs undergo senescence, SIRT6 expression is reduced, which greatly increases the risk of stroke." (PMID 37199574, 2023). "Further studies are needed to determine the direct mechanism underlying SIRT6 function in stroke." (PMID 35855341, 2022). "However, to the best of our knowledge, this is the first report to describe the association between SIRT6 and post-stroke mortality in humans." (PMID 36443316, 2022). "Clinical studies have shown that SIRT6 expression is related to stroke outcomes, as SIRT6 helps maintain the integrity of the blood–brain barrier." (PMID 41180381, 2025). "In a mouse study, vascular SIRT6 expression was reduced following stroke and overexpression of SIRT6 decreased infarct size and neurological deficits." (PMID 37787108, 2023). "Downregulation of SIRT6 has been shown to greatly enhance translocation of HMGB1 from the nucleus to the cytoplasm in stroke models in adult rats." (PMID 37787108, 2023). "Recent research by Camici and colleagues has shown that endothelial-specific SIRT6 aggravates whereas endothelial-specific SIRT6 over-expression ameliorates the incidence and severity of stroke, one of the most common consequences of CHD." (PMID 35246513, 2022). "SIRT6 in ECs attenuates stroke and neurological deficits by maintaining BBB integrity." (PMID 37199574, 2023). "Senescence-associated angiocrine factors from ECs are crucial for neuronal survival and post-stroke regeneration, which may be critical for SIRT6 function in stroke, as AKT controls the angiocrine phenotype." (PMID 35855341, 2022). "ER increased SIRT6 expression, suggesting that ER might exert neuroprotective effect via inducing SIRT6 after stroke." (PMID 35562171, 2022). "Based on this evidence, we hypothesized that circulating levels of SIRT6 could be a predictor of post-stroke mortality in humans." (PMID 36443316, 2022). "Whether SIRT6 functions as a part of the multiprotein complex in the postsynaptic membranes, or it regulates the neurite growth during the post-stroke recovery phase should be further studied." (PMID 34680562, 2021). "Furthermore, preventing stroke by overexpressing SIRT6 is a promising translational strategy." (PMID 35855341, 2022). "SIRT6 was co-expressed with GAP-43, a marker of axon growth and synapse formation, at 14 days after photothrombotic stroke in the mouse cerebral cortex." (PMID 34680562, 2021). "Mice lacking SIRT6 exhibit larger infarct areas during stroke, confirming SIRT6's crucial role in vascular homeostasis." (PMID 41180381, 2025). "Using mice models lacking SIRT6, researchers found that mice lacking SIRT6 exhibited larger stroke size, more severe neurological deficits, and increased blood–brain barrier disruption." (PMID 37627275, 2023).
acute myocardial infarction (11 papers, 2019 to 2024). Necrosis of the myocardium, as a result of interruption of the blood supply to the area. "In supporting of this, myocardial hypoxia/reoxygenation (H/R)-induced injury is significant in mediating the pathogenesis of acute myocardial infarction, and Sirt6 suppresses cell death via NF-kB signaling cascade in myocardial H/R-induced injury." (PMID 37497437, 2023). "For example, myocardial infarction alters the transcriptional activity of Sirt6 gene promoter and influences Sirt6 protein expression levels." (PMID 37497437, 2023). "Previous studies connected Sirt6 with myocardial infarction and enriched our current understandings of interactions between Sirt6 and AMI." (PMID 37497437, 2023). "Recent clinical studies showed that metformin treatment led to improved clinical outcomes for acute myocardial infarction patients with prediabetes by improving SIRT6 expression, which reduced inflammatory factor effects." (PMID 36465178, 2022). "Furthermore, it is reported that metformin therapy mitigates cardiovascular outcomes by improving Sirt6 levels in acute myocardial infarction-prediabetes (AMI-PDM) patients." (PMID 37497437, 2023). "By now, most cell experiments were conducted focusing on ongoing cellular processes that occurs within cardiomyocytes; however, it is intriguing that silencing of Sirt6 also hampers neutrophil penetration in myocardial infarct area and confines infarct area to a small size during reperfusion." (PMID 37497437, 2023). "In addition, in a mouse model, Sirt6 silencing reduced neutrophil infiltration, myocardial infarct size and reactive oxygen species (ROS) generation within infarcted heart tissues in the early phases of I/R." (PMID 36465178, 2022). "Besides, numerous evidence explained that Sirt6 is involved in myocardial infarction." (PMID 37497437, 2023). "Another study indicated that Sirt6-induced autophagy restricted TREM-1-mediated pyroptosis, which renders Sirt6 and TREM-1 inflammatory markers for use in prognosis stratification of acute myocardial infarction." (PMID 38172884, 2024). "Notably, pericoronary fat could over-express the sodium-glucose cotransporter 2 (SGLT2) and leptin, along with decreased sirtuin 6 (SIRT6) expression in PDM vs. normoglycemic (NG) patients undergoing coronary artery bypass grafting (CABG) for acute myocardial infarction (AMI)." (PMID 34440108, 2021). "Furthermore, metformin reduced inflammatory parameters, expression of SGLT-2, and leptin levels from pericoronary fat through the improvement of sirtuin 6 (SIRT6), in people with prediabetes undergoing CABG due to acute myocardial infarction." (PMID 35620570, 2022). "Interestingly, silencing SIRT6 expression and inhibiting NAMPT activity reduced the biosynthesis of the neutrophil chemoattractant CXCL8 in mononuclear cells, thereby attenuating neutrophil infiltration and limiting myocardial infarct size during reperfusion." (PMID 36465178, 2022).
colitis (11 papers, 2018 to 2024). Inflammation of the colon. "Deletion of Sirt6 in IEC resulted in increased susceptibility to dextran sodium sulfate (DSS)-induced colitis in mice." (PMID 39253083, 2024). "FY Liu reported that intestinal epithelial cell-specific knockout of SIRT6 increases susceptibility to dextran sulfate sodium salt (DSS)-induced colitis in mice." (PMID 32580272, 2020). "Loss of SIRT6 causes spontaneous colitis in mice and makes intestinal epithelial cells prone to stress." (PMID 32580272, 2020). "Deletion of SIRT6 in IEC results in increased susceptibility of mice to DSS-induced colitis." (PMID 39253083, 2024). "Notably, IEC-specific Sirt6 knockout mice are more susceptible to dextran sulfate sodium (DSS)-induced colitis." (PMID 36057627, 2022). "SIRT6 is involved in multiple essential biological processes, including genomic stability, inflammation and metabolism, and SIRT6 deficiency, leading to severe colitis in mice and increasing susceptibility to injurious insults in cells, and its overexpression enhances resistance to stress." (PMID 32580272, 2020). "To investigate whether SIRT6 overexpression holds protective effects against DSS-induced colitis, we examined the weight loss, colitis symptoms, histological tissue damage, expression of tight junction-associated proteins, and production of pro-inflammatory cytokines." (PMID 32580272, 2020). "Conversely, overexpression of SIRT6 protects mice from DSS-induced colitis due to reduced activation of NF-κB and c-Jun pathways." (PMID 39253083, 2024). "Citrobacter rodentium infection and dextran sodium sulfate-induced colitis models were used to determine the role of SIRT6 in gut defense." (PMID 39253083, 2024). "The protective effect of SIRT6 in colitis is considered to act by maintaining the R-sponndin-1 level in the colon." (PMID 39253083, 2024). "It has been shown that SIRT6 expression was decreased in IEC during colitis in both mice and humans." (PMID 39253083, 2024). "Mice with SIRT6 deficiency in ILC3s are resistant to C. rodentium infection and DSS-induced colitis." (PMID 39253083, 2024). "We observed increased intestinal pathological damage and inflammation, indicating that spontaneous colitis occurred in SIRT6 KO mice." (PMID 36567449, 2023). "In mouse experimental colitis induced by dextran sulfate sodium salt, SIRT6 overexpression attenuated signs and histological damage in the colon, highlighting SIRT6’s protective effects on the colon." (PMID 38016059, 2023). "A recent animal experiment study showed that SIRT6 overexpression suppressed the phosphorylation of NF-κB in DSS-induced colitis." (PMID 35517808, 2022). "Collectively, these results demonstrated that SIRT6 overexpressed mice showed increased tolerance to DSS-induced colitis and maintained a more normal bowel function." (PMID 32580272, 2020). "Our study reveals that SIRT6 overexpression attenuates DSS-induced colitis and uncovers the protective role of SIRT6 on intestinal function and homeostasis." (PMID 32580272, 2020). "Here, in vivo results demonstrated that SIRT6 overexpression attenuates DSS-induced colitis in terms of clinical manifestations, histopathological damage, loss of tight junction function and imbalanced intestinal microenvironment." (PMID 32580272, 2020). "Taken together, our results reveal the pivotal protective effects of SIRT6 against DSS-induced colitis, mainly through inhibiting the activation of NF-κB and c-Jun by regulating TAK1 signaling." (PMID 32580272, 2020).
colitis (continued). "Our study further supports the conclusion that SIRT6 is indispensable for the maintenance of health and provides a new therapeutic target for colitis." (PMID 32580272, 2020). "(C) Histology of small intestinal cross-sections of WT, Sirt6 KO and compound mutant mice to detect colitis, at the age of ~24 days." (PMID 29474172, 2018). "Studies have shown that SIRT6 plays a protective role in colitis." (PMID 39253083, 2024). "By contrast, overexpressing Sirt6 improved DSS-induced colitis." (PMID 39253083, 2024). "Furthermore, ablation of SIRT6 in ILC3s protects mice against Citrobacter rodentium infection and dextran sodium sulfate-induced colitis." (PMID 39253083, 2024). "We therefore explored whether SIRT6 overexpression influenced the level of pro-inflammatory cytokines in DSS-induced colitis." (PMID 32580272, 2020). "Moreover, there is a decreased expression of colonic SIRT6 in both DSS-induced colitis mouse model and ulcerative colitis patients." (PMID 32580272, 2020). "Therefore, mice with DSS-induced colitis benefit from SIRT1 activation or SIRT6 overexpression." (PMID 37371959, 2023). "Many of the phenotypes associated with SIRT6 deficiency, such as premature aging, colitis and increased IFN expression, were reverted after treatment with RTis, suggesting a central role for the LINE-1/IFN interaction in the disease-associated traits of SIRT6 KO mice." (PMID 33888553, 2021). "Thus, suppressing NF-κB activation by overexpressed SIRT6 contributes to anti-colitis in mice." (PMID 32580272, 2020). "Deletion of SIRT6 in ILC3s resulted in increased IL-22 production and protected mice from C. rodentium infection and DSS-induced colitis." (PMID 39253083, 2024). "SIRT6 transgenic mice showed lower levels of pro-inflammatory cytokines like TNF-a, IL-1β, and IL-6 in the dextran sulfate sodium salt (DSS)-induced colitis model than normal mice." (PMID 35517808, 2022). "SIRT6 is globally overexpressed in TG mice used in this study, so we conjecture that SIRT6 functions in various cells to prevent against DSS-induced colitis in mice." (PMID 32580272, 2020). "However, whether SIRT6 overexpression increases resistance to colitis remains unknown." (PMID 32580272, 2020). "To study the protective capability of SIRT6, we induced a DSS colitis model in mice on day 1 according to the established protocol, with only minor modifications (see Method)." (PMID 32580272, 2020). "FK866, a small NAMPT inhibitor, reduces mucosal NAD+ and NAD+-dependent enzymes (including PARP1, SIRT6, and CD38), NF-κB pathway activation, and inflammatory cell infiltration, thereby improving DSS-induced colitis in mice and preventing inflammation-related tumors." (PMID 37371959, 2023). "Importantly, the protective role of SIRT6 in colitis maybe mediated by R-spondin-1 because SIRT6 fails to prevent proinflammatory cytokines induced YAMC (a normal colonic epithelial cell line) cell death when Rspo1 is silenced by siRNA27." (PMID 36057627, 2022). "However, whether SIRT6 overexpression prevents colitis has not been elucidated." (PMID 32580272, 2020).
Osteopenia (11 papers, 2013 to 2025). Osteopenia is a term to define bone density that is not normal but also not as low as osteoporosis. "Global deletion of the gene encoding a nuclear histone deacetylase sirtuin 6 (Sirt6) in mice leads to osteopenia with a low bone turnover due to impaired bone formation." (PMID 27189179, 2016). "Moreover, in the SIRT6-deficient mice, the degenerative phenotype was promoted and the mice experienced premature aging traits including, but not limited to, kyphosis, and osteopenia which could be explained as a failure in base excision repair." (PMID 37199639, 2023). "A deficiency in SIRT6 causes the hyperacetylation of H3K9 in the Dkk1 promoter, resulting in osteopenia." (PMID 37626845, 2023). "Bone histomorphometry was performed using μCT analysis, which further demonstrated bone growth retardation and severe osteopenia in SIRT6-KO mice." (PMID 27357320, 2016). "Sirt6−/− mice exhibit skeletal abnormalities, such as growth retardation, osteopenia and lordokyphosis." (PMID 24149372, 2013). "Specifically, osteoblast lineage‐specific SIRT6 KO mice established using the osteocalcin promoter exhibited osteopenia, which was attributed to a paracrine activation of osteoclastogenesis due to decreased osteoprotegerin (OPG) levels without changes in osteoblast function." (PMID 33393735, 2021). "Sirt6 knockout mice suffering from osteopenia, exhibited more significant bone loss than the non-mutant mice, indicating that Sirt6 was involved in decreased osteoclast activation." (PMID 33442387, 2020). "In addition, Sirt6−/− mice exhibit osteopenia due to impaired mainly bone formation, with 30% reduction in bone mineral density." (PMID 27189179, 2016). "Sirt6−/− mice also exhibit features of premature aging, such as osteopenia and lordokyphosis." (PMID 24149372, 2013).
metabolic syndrome (10 papers, 2018 to 2024). A cluster of metabolic risk factors for CARDIOVASCULAR DISEASES and TYPE 2 DIABETES MELLITUS. "In one rodent model of metabolic syndrome, hepatic SIRT6 was positively associated with SIRT1 and was found to improve blood lipid profiles to protect against adipose-induced oxidative stress." (PMID 35805129, 2022). "Chrysophanol has been shown to upregulate SIRT6 expression, alleviating metabolic syndromes mediated through the SIRT6/AMPK signaling pathway." (PMID 36465178, 2022). "An analysis of 29 severely obese patients associated with metabolic syndrome found that weight loss resulted in the activation of SIRT1, SIRT3, and SIRT6 expression in hepatic and adipose tissue." (PMID 35805129, 2022). "These authors demonstrated that hepatic-specific deletion of SIRT6 resulted in increased blood glucose and hepatic steatosis, inducing metabolic syndrome." (PMID 35805129, 2022). "This study is aimed at evaluating the relationship between liver SIRT6 gene expression and the oxidative stress network depending on adiposity levels in Zucker rats, an animal model of metabolic syndrome." (PMID 30671172, 2018). "Therefore, the aim of this study was to evaluate the hepatic gene expression of SIRT6 and its relationship with the oxidative stress network depending on adiposity levels in Zucker rats, an animal model of metabolic syndrome." (PMID 30671172, 2018). "The expression of SIRT1 and SIRT6 is downregulated in lipid metabolism-related diseases, and the expression of SIRT1 is downregulated in metabolic syndrome, which exerts an adverse effect on metabolic health." (PMID 36581622, 2022). "Therefore Sirt6 could be a potential target in the treatment of dyslipidemia." (PMID 33442387, 2020).
Parkinson’s (10 papers, 2016 to 2025). "New findings also suggest that the changes observed in SIRT6-deficient brains also occur in the aging human brain, particularly in patients with Alzheimer’s, Parkinson’s, and Huntington’s diseases and amyotrophic lateral sclerosis." (PMID 38612681, 2024). "We also identify SNPs that promote SIRT6 expression and simultaneously associate with an increased risk of Parkinson’s." (PMID 30409187, 2018). "Our data suggest that SIRT6 plays a pathogenic and pro-inflammatory role in Parkinson’s and that nicotine can provide neuroprotection by accelerating its degradation." (PMID 30409187, 2018). "Importantly, the changes we observed in SIRT6-deficient brains are also occurring in aging human brains and particularly in patients with Alzheimer’s, Parkinson’s, Huntington’s, and Amyotrophic lateral sclerosis disease." (PMID 36653345, 2023). "We showed that REST was overexpressed in SIRT6-KO brains and cells; however, it was inactive, similar to what is observed in patients with AD and Parkinson’s." (PMID 39511137, 2024). "For instance, inhibiting SIRT6 was suggested as a promising strategy against Parkinson’s disease, given that SIRT6 has pro-inflammatory effects in this disorder and thereby accelerates its course." (PMID 32736564, 2020). "This study suggests a mechanistic explanation for how tobacco users are protected from Parkinson’s and how the tobacco component nicotine confers neuroprotection; more specifically, nicotine suppresses SIRT6 which confers resistance to neuron and cell death." (PMID 30409187, 2018). "Furthermore, brain-specific SIRT6 knockout mice are protected from MPTP-induced Parkinson’s, while SIRT6 overexpressing mice develop more severe pathology." (PMID 30409187, 2018). "Additionally, SIRT6 abundance is greater in Parkinson’s patient brains, and decreased in the brains of tobacco users." (PMID 30409187, 2018). "Inhibition of SIRT6 may be a promising strategy to ameliorate Parkinson’s and neurodegeneration." (PMID 30409187, 2018). "SIRT6 and SIRT7 regulate TNFα, and reduced activity leads to Parkinson’s disease." (PMID 33668997, 2021).